CHDH (choline dehydrogenase)
Diseases named in the same sentence as CHDH in open-access papers (continued):
Sharing a sentence is not in itself a finding about the gene and the disease.
infection (3 papers, 2020 to 2025). The state of being infected such as from the introduction of a foreign agent such as serum, vaccine, antigenic substance or organism. "Contributing to amine and polyamine biosynthesis, the choline dehydrogenase plays a role in barley infection by P. teres." (PMID 33889162, 2021). "Other genes involved in oxidation-reduction processes and defense mechanisms in plants including FAD-binding domains proteins, a choline dehydrogenase, or an iso-amyl alcohol oxidase were upregulated during the infection of barley by P. teres." (PMID 33889162, 2021). "To understand the possible roles of pathogen genes in host infection, we characterized some up‐regulated fungal DEGs, including BCIN_12g01020 encoding oxaloacetate acetylhydrolase (OAH) and BCIN_03g01540 encoding choline dehydrogenase." (PMID 32301267, 2020).
metabolic disorders (3 papers, 2023 to 2025). "CHDH catalyzes the initial step in the oxidation of choline to betaine, and genetic variation in CHDH has been implicated in metabolic disorders." (PMID 41415850, 2025). "In this review, we will summarize the genomic localization, protein structure and basic functions of CHDH and discuss the progress of CHDH research in metabolic disorders and other diseases." (PMID 37600654, 2023). "Here we summarized the genomic localization, protein structure and basic functions of CHDH and discuss the progress of CHDH research in metabolic disorders and other diseases." (PMID 37600654, 2023).
adenocarcinoma (1 paper, 2024). A common cancer characterized by the presence of malignant glandular cells. "Parallel to that, 5 proteins were expressed lower in SOL adenocarcinomas and the low expression of which was correlated with poor OS, including PIGR, CHDH, NAPSA, PLEKHA7 and SELENBP1." (PMID 38182978, 2024).
psychiatric disorder (1 paper, 2019). A disorder characterized by behavioral and/or psychological abnormalities, often accompanied by physical symptoms. "The non-coding SNP rs893363, located in the 3′ UTR of CACNA1D and the putative promoter region of the choline dehydrogenase gene (CHDH), was found in a genome-wide analysis of five major psychiatric disorders including BD, SCZ, ADHD, MDD, and ASD." (PMID 31331039, 2019).
CHDH also shares sentences with these, for which no sentence is quoted: autism (4 papers); neurodevelopmental disorder (3); esophageal cancer (2); gastric cancer (2); homocystinuria (2); Intellectual disability (2); metabolic syndrome (2); bladder cancer (1); cardiovascular diseases (1); CHARGE syndrome (1); cystic kidney disease (1); depression (1); developmental delay (1); diabetes (1); DiGeorge syndrome (1); heart failure (1); melanoma (1); metastatic melanoma (1); Obesity (1); periodontitis (1); prostate carcinoma (1); Speech apraxia (1); ulcerative colitis (1).